GLS (glutaminase)
Diseases named in the same sentence as GLS in open-access papers (continued):
Sharing a sentence is not in itself a finding about the gene and the disease.
tumor (continued). "Glutaminase was injected into mice bearing experimental tumours to reduce blood levels of glutamine; some animals also received 15 Gy radiation to their tumours to assess the effects of glutamine levels on surviving nutrient-deprived (i.e. hypoxic) cells." (PMID 3801270, 1986). "Upregulation of glutaminase enzymatic activity promotes tumour cell proliferation." (PMID 41898641, 2026). "Potentially, plasticity of AAT expression could serve as a marker for cell sensitivity to AAT and GLS inhibition, and tumor cells with less transporter plasticity may be more sensitive to such inhibition." (PMID 40707944, 2025). "GLS inhibitors like CB-839 can reduce glutamine availability for tumor cells." (PMID 40469185, 2025). "In addition, within the co-culture system, A549-shGLS cells exhibited a significantly higher apoptosis rate compared to control cells, further demonstrating that GLS inhibition enhances the tumor-killing effect of immune cells." (PMID 40308578, 2025). "Spatial co-localization of polyamines, fatty acids, and key metabolic genes such as FASN and GLS suggested coordinated metabolic reprogramming that may drive tumor progression and immune modulation." (PMID 40557160, 2025). "Importantly, since aspirin treatment exposes metabolic vulnerabilities in tumor cells, there is an opportunity to combine aspirin with specific metabolic inhibitors, such as glutaminase inhibitors." (PMID 40453660, 2025). "For instance, when GLS inhibitors (e.g., CB-839) are combined with immune checkpoint inhibitors, tumor cells may activate alternative metabolic routes, such as the glutamine synthesis pathway, to circumvent the metabolic stress induced by GLS inhibition." (PMID 41293169, 2025). "Glutamate can then be metabolized either to GSH by GCLC or to 2‐OG by GLUD1 and then enter the TCA cycle.[10b] To find out which metabolic pathway(s) downstream of GLS plays a primary role in regulating tumor antigen presentation, we performed in silico metabolic flux analysis using TCGA datasets." (PMID 39482885, 2025). "Combining GLS inhibitors with targeted therapy can suppress glutamine production and asparagine synthesis via their respective metabolic pathways, restoring tumor cell sensitivity to ASNase and significantly reducing asparagine levels, thereby increasing therapeutic efficacy." (PMID 41179661, 2025). "Notably, curcumin treatment suppressed the expression of lipid and polyamine biosynthetic enzymes (e.g., FASN, SCD, GLS), indicating a broad reconfiguration of tumor metabolic networks." (PMID 40557160, 2025). "Furthermore, GLS has been identified as the first rate-limiting enzyme in glutamine metabolism, which has emerged as a potential therapeutic target for tumours." (PMID 40598593, 2025). "Since glutamine is less critical for T-cell function than for tumor cells, GLS inhibition may preferentially affect cancer cells and improve immune responses." (PMID 40469185, 2025). "GLS plays a pivotal role in glutamine metabolism and supports tumour growth." (PMID 41050056, 2025). "Although preclinical studies suggest that targeting glutamine pathways—such as through glutaminase inhibition—can suppress tumor progression and neovascularization, the clinical relevance of these findings in the context of perioperative supplementation remains uncertain." (PMID 40806373, 2025). "However, a pertinent challenge has been encountered in practical application, where the sole inhibition of glutaminase blockade leads to tumour cell resistance." (PMID 41515893, 2025). "It is found that GLS knockdown in CRC cells enhanced the cytotoxicity of tumor‐specific T cells." (PMID 39482885, 2025). "Combined metabolic intervention: The combination of CPS1 inhibitors and GLS inhibitors may simultaneously disrupt tumor ammonia detoxification barriers and alleviate ammonia toxicity in CD8+ T cells." (PMID 41041303, 2025).
tumor (continued). "Also, various in vitro studies have revealed that the activity of glutaminase against the proliferation of tumor cell lines using the MTT (3-(4,5- dimethylthiazol-2-yl)- 2, 5-diphenyltetrazolium bromide) cell proliferation assay." (PMID 39905290, 2025). "We hypothesized that GLS inhibition should induce tumor radiosensitization due to increased oxidative stress." (PMID 40707944, 2025). "Additionally, Western blot and IHC analysis of tumor tissues revealed a marked reduction in GPX4 expression in the GLS-knockdown group, suggesting an enhanced level of ferroptosis." (PMID 40308578, 2025). "Therefore, the metabolism of glutamine can be affected by lncRNA and GLS, thus playing an important role in tumor metabolic reprogramming." (PMID 39539540, 2024). "In addition, researchers have developed a multifunctional biomimetic nanoplatform (referred to as HM-BPT), which utilizes pH-sensitive tumor-targeting hybrid membrane-coated manganese oxide nanoparticles for the delivery of the glutaminase inhibitor BPTES." (PMID 38459595, 2024). "Considering that GLS knockout enhances cuproptosis sensitivity, targeting GLS could be a beneficial strategy to counteract the drug or radioresistance of tumor cells." (PMID 38918694, 2024). "LncRNAs play an essential role in glutamine metabolic reprogramming and serine/glycine metabolism in GI tract tumor cells, mainly by acting through the glutamine metabolism-related key enzymes GLS and GDH and the serine/glycine metabolism-related key enzyme SHMT2." (PMID 38184562, 2024). "The differential expression in distinct subtypes of specific tumor types might provide new and meaningful entry points for further exploration of the oncogenic role of GLS." (PMID 38566121, 2024). "According to the tumor heterogeneity analysis, we found that GLS expression was most negatively correlated with TMB in CHOL (r = -0.51), which indicated that down-regulated GLS might serve as a breakthrough for enhancing immunotherapy in CHOL." (PMID 38566121, 2024). "For example, although targeting tumor metabolism of glutamine by GLS inhibition could theoretically block the herein studied mechanism of metabolic reprogramming, the clinically applicable GLS inhibitor CB-839 has very low BBB permeability." (PMID 38811525, 2024). "Therefore, experiments on the combination of mTOR and GLS inhibitors have been conducted, and they have shown anti-tumor effects in xenograft models." (PMID 38895635, 2024). "We hypothesized that the higher glutaminase activity of PegC compared to E. coli-derived asparaginases may be advantageous as it was recently reported that the anti-tumor activity of asparaginases in PDAC is dependent on its glutaminase activity." (PMID 38951899, 2024). "Glutaminase is a promising target for treating many tumor types." (PMID 38965208, 2024). "Current strategies targeting tumor glutamine metabolism include systemic glutamine depletion, glutamine consumption within the tumor microenvironment, glutamine uptake inhibitors, glutamine antimetabolites, and glutaminase inhibitors." (PMID 39075485, 2024). "Additionally, glutaminase-mediated production of glutamate can contribute to the generation of ROS, which can promote DNA damage and genomic instability, further facilitating tumor progression." (PMID 39170262, 2024). "Glutaminase 1 (GLS1), which converts glutamine into glutamate, is a key enzyme in tumor cell metabolism because it can promote lipid and nucleotide biosynthesis and reduce ROS generation, thereby protecting tumor cells from apoptosis." (PMID 36835122, 2023). "bis-2-(5-phenylacetamido-1,3,4-thiadiazol-2-yl) ethyl sulfide (BPTES) and CB-839, GLS inhibitors are confirmed to have anti-tumor effective; especially CD839 has been proved to possess the ability of antiproliferative activity in both solid tumors like pancreatic cancer and breast cancer." (PMID 37635935, 2023).
tumor (continued). "Also, aspartate has been suggested to be a limiting metabolite for tumor growth and cell proliferation under hypoxic conditions, and reduced aspartate levels increase the dependence on glutaminase to replenish the TCA cycle." (PMID 36914921, 2023). "Our observation showed that after intervening with si-GLS, the expression levels of both E-cadherin and N-cadherin were significantly decreased, indicating a promoting effect on the pathway, and so the metastasis of the tumor." (PMID 37664031, 2023). "Finally, low GOT2 expression resensitizes tumour cells to glutaminase inhibitors, to increase the effect of targeted glutamine on tumours." (PMID 37829798, 2023). "In addition, we observed an increase in glutamate and a decrease in glutamine in the tissues and serum of ESCC patients, suggesting enhanced glutaminase activity for tumor development." (PMID 36756157, 2023). "Importantly, the combined inhibition of mTOR kinase and glutaminase (GLS) profoundly reduces tumor growth in a GBM xenograft model." (PMID 37108511, 2023). "Clearly, inhibition of GLS2 activity may reduce the survival of those cells in which GLS protein acts as a tumor promoter." (PMID 38067269, 2023). "Cold atmospheric plasma treatment could significantly alter the metabolite profiling of tumor cells, such as the beta-alanine metabolic pathway, glutaminase activity, and glucose metabolites." (PMID 35327329, 2022). "Glutaminase therefore serves as a logical target for inhibition of tumor metabolism, and preclinical studies of the glutaminase inhibitor CB-839 demonstrated efficacy in slowing tumor cell growth." (PMID 36203456, 2022). "Among them, MTHFD1L and GLS have been reported to be tumor-promoting in HCC32,33." (PMID 35710796, 2022). "Therefore, the glutaminase inhibitor CB-839 enhances the function of Teff cells while inhibiting the function of Treg cells, thereby enhancing the anti-tumor immune response." (PMID 35897036, 2022). "The intervention in glutamate metabolism by glutaminase inhibitors was shown to impact glutathione levels, which could reduce the antioxidative tumor capacity." (PMID 36355130, 2022). "Additionally, YTHDF1 was found to rewire tumor metabolism by promoting the protein translation of glutaminase 1 (GLS1) by targeting the 3′UTR of GLS1 mRNA, which contributes to chemoresistance to cisplatin." (PMID 35884552, 2022). "Importantly, succinylation of tumor-highly expressed GLS and glutaminolysis in PDAC are governed by dynamical association of GLS with SUCLA2, which confers tumor cells greater capacity to counteract oxidative stress and support tumor growth." (PMID 34913133, 2022). "Moreover, constitutive NRF2 activity also confers sensitivity to glutaminase inhibition, thus preventing the reactivation of dormant tumor cells in vitro." (PMID 35158815, 2022). "At the same time, protein acetylation has emerged as a prevalent posttranslational modification (PTM) in mitochondria to modulate enzymatic activity, and whether mitochondrial GLS acetylation is modulated to support hepatic tumour cell growth remains unknown." (PMID 35538890, 2022). "GLS inhibition may also limit the pro‐tumor IL‐17 secretion, which further potentiates the anti‐tumor effects of JHU083." (PMID 35861366, 2022). "The activities of different isoforms of glutaminase, which is involved in the glutathione-dependent antioxidant defense system of the cell, could either promote tumor progression or suppress it through certain pathways involving miRNAs." (PMID 36552527, 2022). "The clinical shortcomings of glutaminase inhibition to slow tumor growth may be based in the adaptable nature of tumor metabolism." (PMID 36203456, 2022). "Importantly, chemotherapeutic drug delivery and therapeutic efficacy were improved in tumor-bearing GLSECKO hosts or in combination with GLS inhibitor, CB-839." (PMID 36381236, 2022).
tumor (continued). "In addition, elevated GLS expression has been associated with high grade and metastatic breast cancer and inhibition of GLS activity or gene expression prevents oncogenic transformation and tumor growth." (PMID 35299741, 2022). "It has been demonstrated that tumor cells can route glutamine through the tricarboxylic acid (TCA) cycle in reverse via a pivotal mitochondrial glutaminolytic amidohydrolase enzyme known as glutaminase (GLS)." (PMID 36139432, 2022). "Several inhibitors exist that may hold some therapeutic potential, such as the GLS inhibitor CB-839, which is currently in clinical trials for anti-tumor potential and can be repurposed for the treatment of OA." (PMID 35916374, 2022). "Notably, ccRCC relies on glutamine for tumour growth, which has led to the investigation of the glutaminase (GLS) inhibitor CB‐839 in a phase I clinical study with patients with advanced/metastatic ccRCC." (PMID 35678045, 2022). "Interestingly, liver–enriched glutaminase 2 (GLS2) appears to play a greater role than ubiquitous and canonical tumour–enriched glutaminase 1 (GLS1) in promoting murine HCC." (PMID 35538890, 2022). "However, a combination of GLS deletion in host vessels with Cpt administration further decreased tumor growth relative to WT tumor growth (∼4-fold at day 25)." (PMID 36381236, 2022). "Interestingly, MTF1, PDHB and GLS were reported to be highly expressed in other tumor types, while in our study, we found that these genes were strongly associated with good prognosis." (PMID 36620594, 2022). "Depletion of EPB41L4A-AS1 largely increases the anti-tumor effect of glutaminase inhibitors." (PMID 35707366, 2022). "To investigate clinical relevance of GLS inhibition in the tumor blood vessels, we tested whether pharmacologic inhibition of GLS can improve efficacy of chemotherapy." (PMID 36381236, 2022). "Knockdown of glutaminase-1 (GLS1) resulted in inhibition of tumor growth." (PMID 35091542, 2022). "For example, CB-839, the inhibitor of glutaminase (GLS) could exert strong anti-tumor effects alone or in combination with targeted therapy in ccRCC cell lines." (PMID 36313638, 2022). "It remains to be established whether this glutaminase co-activity is truly required for a long-term antileukemic response in ASNS-negative tumor cells." (PMID 35205650, 2022). "Interestingly, the levels of GCN5L1 inversely correlated with mTORC1 activity and glutaminase activity in these tumours." (PMID 35538890, 2022). "This vital function of glutaminase in glutaminolysis makes it a promising target for tumor therapy." (PMID 35864951, 2022). "In addition, GLS plays an important role in the phenotypic changes in the endothelial–mesenchymal transition (EMT) of tumor cells and CAFs." (PMID 34503536, 2021). "Moreover, miR-513c, as a tumor suppressor, plays an important role in regulating glutamine metabolism by targeting GLS." (PMID 34233668, 2021). "It was found that the glutaminase activity of He plasma jet group was lower than that of surface plasma group, which might be a reason for He plasma jet group to kill tumor cells better." (PMID 33816218, 2021). "In addition, our data suggested that the expression levels of ATP11 C, CSE1L, SLC39A14, SLCO5A1, and GLS were higher in tumor tissues than in normal tissue by a factor of 3.4, 4.7, 2.8, 1.7 and 3.6, respectively." (PMID 34516344, 2021). "Moreover, the level of GLS was frequently elevated in tumor samples compared to the level of GS, suggesting a metabolic flux from glutamine to glutamate for the high rates of glutamine catabolism." (PMID 32013066, 2020). "First, GLS inhibitor CB839 was injected 2 times a week within the tumor bed of HOT-bearing mice." (PMID 32789014, 2020). "Glutamine supplementation may also decrease tumor glutaminase activity and tumor glutathione; this then may inhibit tumor utilization of glutamine for fuel and also make tumors more susceptible to damage from intracellular chemotherapy metabolites." (PMID 32512833, 2020).
tumor (continued). "Publicly available mRNA expression data showed that GLS is markedly overexpressed in the leading edge of the tumor and infiltrating tumor tissue and it is thought that these tumor compartments promote GSC enrichment through a mechanism called epithelial–mesenchymal (EMT)-like transition." (PMID 32337072, 2020). "Based on our in vitro findings we sought to evaluate the expression level of GLS-1 in Pheo/PGLs tumor tissues in order to assess whether GLS-1 expression might serve as a marker for malignancy in Pheo/PGLs." (PMID 32150977, 2020). "Yet, whether these extrinsic factors contribute to the decrease in glutamine metabolism observed in many tumours compared with in vitro conditions and the potential impact on antitumour activity of glutaminase inhibitors is unknown." (PMID 32450839, 2020). "Increased activity of pyruvate carboxylase has been reported as a potential metabolic mechanism for tumor growth in situations where GLS activity is challenged, although growing the cells in glucose-free media for 72 h did not affect significantly the viability nor the growth of CB839-treated cells." (PMID 33101674, 2020). "Furthermore, compound 968 (C968), another small molecule GLS inhibitor, has been reported to impair tumor cell clonogenicity, viability, and growth." (PMID 32337072, 2020). "Additionally, the recently described in situ GLS overexpression in RMS samples suggests a high glutamine demand of in vivo tumor growth." (PMID 32709151, 2020). "Additionally, it is possible that the environment and metabolic milieu accompanying the tumor is responsible for the apparent resistance to glutaminase inhibition." (PMID 32937954, 2020). "Our data suggests that GLS-1 inhibition in SDH deficient chromaffin cells tumors may represent novel, tumor specific alternatives of therapy in malignant Pheo/PGL where the current treatment options are limited." (PMID 32150977, 2020). "Elevated glutaminase and glutamate levels following mTOR (mammalian target of rapamycin) kinase inhibitor treatment promoted GBM survival while combined inhibition of mTOR kinase and glutaminase resulted in massive synergistic tumor cell death and growth inhibition." (PMID 32708312, 2020). "Moreover, the accumulation of glutamine, as a result of GLS inhibition, has been shown to induce divergent metabolic programs to overcome tumor immune evasion." (PMID 32937954, 2020). "We showed that the metabolic reprogramming induced by both PDK and glutaminase inhibitors could affect tumor angiogenesis." (PMID 33076309, 2020). "Moderate to strong GLS immunostaining was seen in most tumor cells (mainly cytoplasm and nucleus) and the stain was clean with no background except in cases that had lymphocytes in the core along with the tumor cells." (PMID 31428575, 2019). "Moreover, we also demonstrate that, along this pathway, mitochondrial GLS, involved in the first step of glutamine metabolism and often overexpressed in tumour cells, is a target of metformin." (PMID 30646605, 2019). "In vivo tumorigenesis experiments revealed significant decreases in tumor growth, tumor weight, and Ki67-positive staining upon silencing of GLS, GOT2, or ASNS in SW480-SOX12 cells, whereas GLS, GOT2, or ASNS overexpression reversed the SOX12 knockdown-induced suppression of tumor growth." (PMID 30858360, 2019). "To determine whether loss of Ldh activity promotes glutamine metabolism, we measured glutaminase activity in tumor lysate." (PMID 30626875, 2019). "Indeed, GLS activity and glutamine anaplerosis is dispensable in GSCs expressing Glutamine synthetase (GS), which controls glutamine homeostasis by catalyzing the opposite reaction of GLS and is highly expressed in GSCs as compared to tumor cells." (PMID 30895167, 2019).